POU3F3 (POU class 3 homeobox 3)
Diseases named in the same sentence as POU3F3 in open-access papers (continued):
Sharing a sentence is not in itself a finding about the gene and the disease.
esophageal cancer (4 papers, 2015 to 2025). A primary or metastatic malignant neoplasm involving the esophagus. "Another lncRNA secreted by esophageal tumor cells, POU3F3, is also found to be upregulated in advanced esophageal cancer with resistance to cisplatin, another chemotherapeutic drug widely used for esophageal cancer treatment." (PMID 40781643, 2025). "In esophageal cancer, the lncRNA POU3F3 is secreted by tumor cells and incorporated into exosomes, which are then taken up by fibroblasts." (PMID 40781643, 2025). "Specifically, CAFs activated by exosomal POU3F3 secrete interleukin-6, a cytokine that promotes resistance to cisplatin, a common chemotherapeutic drug for esophageal cancer." (PMID 40781643, 2025). "In the present study, 10 lncRNAs (HOTAIR, AFAP1-AS1, POU3F3, HNF1A-AS1, 91H, PlncRNA1, SPRY4-IT1, ENST00000435885.1, XLOC_013104 and ENST00000547963.1) that were previously reported with deregulated expression in esophageal cancer were selected as candidate diagnostic makers." (PMID 25608466, 2015). "Oncogenic lncRNAs FOXD2-AS1, POU3F3, and LINC00337 were revealed to be involved in DDP resistance of esophageal cancer." (PMID 34881242, 2021). "Ten lncRNAs (HOTAIR, AFAP1-AS1, POU3F3, HNF1A-AS1, 91H, PlncRNA1, SPRY4-IT1, ENST00000435885.1, XLOC_013104 and ENST00000547963.1) which previously found to be differently expressed in esophageal cancer were selected as candidate targets for subsequent circulating lncRNA assay." (PMID 25608466, 2015). "On the basis of previous study, 10 lncRNAs (HOTAIR, AFAP1-AS1, POU3F3, HNF1A-AS1, PlncRNA1, SPRY4-IT1, ENST00000435885.1, ENST00000547963.1, 91H and XLOC_013104) which have been reported to be differently expressed in esophageal cancer were selected in the present study." (PMID 25608466, 2015).
gastric cancer (4 papers, 2018 to 2023). A primary or metastatic malignant neoplasm involving the stomach. "Linc-POU3F3 facilitates the distribution of Treg cells among peripheral T cells, which caused increased cell proliferation of gastric cancer cells through recruiting TGF-beta and activating TGF-beta pathway." (PMID 30546835, 2018). "Accordingly, elevated levels of long intergenic noncoding RNA POU3F3 (linc-POU3F3) in gastric cancer (GC) patient-derived Tregs augments Treg distribution, through modulation of TGF-β signaling pathway, while lncRNA Flatr enhances the immunosuppressive function of Tregs by boosting FOXP3 expression." (PMID 34943820, 2021). "LncRNAs linc-POU3F3 and RP11-323N12.5 are both associated with gastric cancer (GC)." (PMID 37346034, 2023). "Linc-POU3F3 promotes Treg cell proliferation by binding TGF-β and inducing TGF-β/SMAD signaling in gastric cancer." (PMID 37346034, 2023).
lung carcinoma (4 papers, 2016 to 2025). "The data exhibited that POU3F3 was upregulated in lung cancer tissue compared with that in paracancerous tissue." (PMID 39932442, 2025). "Together, these data demonstrated that POU3F3 was highly expressed in lung cancer and correlated with the poor prognosis, suggesting that POU3F3 protein expression level is crucial for NSCLC progression and transformation." (PMID 39932442, 2025). "To validate these findings, we performed immunohistochemistry (IHC) staining and found that the expression of POU3F3 was significantly higher in lung cancer tissue than that in paired adjacent normal tissue." (PMID 39932442, 2025). "Our study demonstrates the oncogene POU3F3 is overexpressed in NSCLC tissues and cell lines, high POU3F3 expression indicates an unfavorable prognosis for the lung cancer patients." (PMID 39932442, 2025). "Moreover, Kaplan‐Meier analysis displayed that higher POU3F3 mRNA expression is significantly associated with shorter OS and PFS in lung cancer patients." (PMID 39932442, 2025). "POU3F3 is significantly upregulated in non‐small cell lung cancer (NSCLC)." (PMID 39932442, 2025).
Cognitive impairment (3 papers, 2020 to 2025). Abnormal cognition is characterized by deficits in thinking, reasoning, or remembering. "Clinical presentations of POU3F3 mutations vary from cognitive impairment and malformation of several organs." (PMID 36861062, 2023). "Humans with mutations of the POU3F3 gene display a wide range of features directly linked to the size of the mutation spanning from mild cognitive impairment and mild dysmorphosis to complex malformation of the kidney, corpus callosum, heart and anus." (PMID 32397610, 2020).
Intellectual disability (3 papers, 2016 to 2021). "The human Pou3f3 is an intronless gene also named Brain-1, which is a well-known transcription factor involved in the development of the central nervous system and its variant alleles have been associated with intellectual disability and language neurodevelopmental disorders." (PMID 34306008, 2021). "In humans, a heterozygous de novo 360 kb deletion in chromosome band 2q12.1 resulting in the loss of the genes POU3F3 and MRPS9 was identified in a two-year-old boy with mild dysmorphic features of the head, mild motor delay and mild intellectual disability." (PMID 27003440, 2016). "The two other genes POU3F3 and SOX3 are previously reported to be involved in Central Nervous System Tuberculosis and Mental retardation, respectively." (PMID 29101382, 2017).
nasopharyngeal carcinoma (3 papers, 2019 to 2021). A carcinoma arising from the nasopharyngeal epithelium. "Up-regulation of plasma lncRNA POU3F3 led to promoted nasopharyngeal carcinoma cell migration and invasion possibly by up-regulating TGF-β1." (PMID 30602452, 2019). "In the present study, we showed that lncRNA POU3F3 promoted cancer cell migration and invasion in nasopharyngeal carcinoma possibly by up-regulating TGF-β1." (PMID 30602452, 2019). "Our in vitro experiments also showed that lncRNA POU3F3 overexpression promoted the migration and invasion of nasopharyngeal carcinoma cells." (PMID 30602452, 2019). "RT-qPCR results showed that plasma levels of lncRNA POU3F3 were increased in nasopharyngeal carcinoma (NC) patients (P<0.05)." (PMID 30602452, 2019). "In the present study, we showed that plasma levels of lncRNA POU3F3 were also increased in patients with nasopharyngeal carcinoma." (PMID 30602452, 2019). "In the present study, we showed that lncRNA POU3F3 was also up-regulated in plasma of nasopharyngeal carcinoma patients." (PMID 30602452, 2019). "In nasopharyngeal carcinoma, POU3F3 activates TGF-β1 to promote cancer cell invasion and migration." (PMID 35201451, 2021). "In conclusion, lncRNA POU3F3 was up-regulated in nasopharyngeal carcinoma." (PMID 30602452, 2019). "Our follow-up study revealed that high plasma level of lncRNA POU3F3 may serve as a biomarker for the poor prognosis of nasopharyngeal carcinoma, which may provide guidance for clinical studies." (PMID 30602452, 2019). "Therefore, lncRNA POU3F3 may promote cancer cell migration and invasion in nasopharyngeal carcinoma by up-regulating TGF-β1." (PMID 30602452, 2019). "Our study showed that plasma levels of lncRNA POU3F3 and TGF-β1 (transforming growth factor-β) were both increased in nasopharyngeal carcinoma patients than in healthy controls." (PMID 30602452, 2019). "LncRNA POU3F3 overexpression and exogenous TGF-β1 treatment led to promoted, while TGF-β1 inhibitor led to inhibited migration and invasion of nasopharyngeal carcinoma cells." (PMID 30602452, 2019). "A significantly positive correlation between plasma levels of lncRNA POU3F3 and TGF-β1 was observed in nasopharyngeal carcinoma patients." (PMID 30602452, 2019).
osteosarcoma (2 papers, 2018 to 2025). A usually aggressive malignant bone-forming mesenchymal neoplasm, predominantly affecting adolescents and young adults. "We found that knock-down of NR2F1-BT and NR2F1 or POU3F3-BT and POU3F3 similarly reduced the invasion/migration potential of U251MG glioblastoma and U2OS osteosarcoma cells." (PMID 29540241, 2018).
schizophrenia (2 papers, 2019 to 2024). A major psychotic disorder characterized by abnormalities in the perception or expression of reality. "We identified 26 and 27 schizophrenia-associated HC ELEs containing POU3F3 and HAND1::TCF3-binding motifs respectively, further suggesting 86 unique putative target genes." (PMID 38167462, 2024). "Interestingly, two other POU domain transcription factors, Pou3f2 and Pou3f3 are suspected to be involved in schizophrenia due to their effect on cortical neuron migration." (PMID 31787878, 2019). "The 105 schizophrenia-associated HC ELEs show strong enrichments of motifs recognized by POU3F3 and HAND1::TCF3 complex, all of which are relevant to schizophrenia." (PMID 38167462, 2024).
-Fisher syndrome (1 paper, 2025). "The 2q12.1q12.3 region of our patients encompasses 30 protein-coding genes, with POU3F3 emerging as the strongest candidate due to its association with Snijders Blok-Fisher syndrome, characterized by DD, ID, and neurological anomalies." (PMID 40626178, 2025).
cardiomyopathies (1 paper, 2020). "Specifically, post-natal knockdown of Esrrg in mice resulted in cardiomyopathies and arrested mitochondrial maturation; homozygous deletion of Pou3f3 (Brn1) was associated with neonatal mortality and developmental defects in forebrain and kidney." (PMID 33332446, 2020).
colon cancer (1 paper, 2025). "Indeed, 6 out of 10 leading TFs have direct evidence and some experimental validation of their involvement in colon cancer risk and progression: ZNF334, FOXD2, FOXD3, POU3F3, NR1H4, and VSX2." (PMID 41114645, 2025).
cutaneous melanoma (1 paper, 2021). A primary melanoma arising from atypical melanocytes in the skin. "After obtaining complete clinical information from the TCGA database, we assessed the clinical significance of the lncRNA POU3F3 expression in 309 patients with cutaneous melanoma." (PMID 33816296, 2021).
dilated cardiomyopathy (1 paper, 2017). Cardiomyopathy which is characterized by dilation and contractile dysfunction of the left and right ventricles. "The targets of the remaining MRs, e. g., SOX3 and POU3F3, were enriched for Dilated cardiomyopathy (P = 0.0308), Hedgehog signaling pathway (p = 0.0127), Intestinal immune network for IgA production (p = 0.0094), Axon guidance (p = 0.0389), and Vascular smooth muscle contraction (p = 0.0488)." (PMID 29101382, 2017).
epilepsy (1 paper, 2023). A brain disorder characterized by episodes of abnormally increased neuronal discharge resulting in transient episodes of sensory or motor neurological dysfunction, or psychic dysfunction. "For example, epilepsy was more common in patients with a non-truncating variant of POU3F3 (4/17, 23.53%), while only one patient had epilepsy in 27 patients with a truncating variant of POU3F3 (1/27, 3.70%)." (PMID 37593446, 2023).
gastric tumors (1 paper, 2018). "Further, we observed the association of Linc-POU3F3 overexpression in gastric tumors from patients with non-vegetarian diet habit (P = 0.043)." (PMID 29719612, 2018). "Consistent with our results, we also found overexpression of lncRNAs such as H19, GAS5, TUG1, AP5M1 and MALAT1 and downregulation of LINCROR, POU3F3, HOTAIR, FALEC, NBAT1, and ZEB2-AS1 lncRNAs in TCGA gastric tumor datasets." (PMID 29719612, 2018).
lung squamous cell carcinoma (1 paper, 2020). "Our future studies will explore the role of POU3F3 in lung squamous cell carcinoma." (PMID 32615948, 2020).
metastatic tumors (1 paper, 2021). "Further analysis showed an increased lncRNA POU3F3 expression in the metastatic tumors than in the localized ones (p = 0.01)." (PMID 33816296, 2021).
neuroblastoma (1 paper, 2014). Neuroblastoma (NB) is the most common solid, extracranial childhood tumor. "Daliis transcribed downstream of the Pou3f3 transcription factor geneand its depletion disrupts the differentiation of neuroblastoma cells." (PMID 25415054, 2014).
non-small cell lung carcinoma (1 paper, 2020). A group of at least three distinct histological types of lung cancer, including non-small cell squamous cell carcinoma, adenocarcinoma, and large cell carcinoma. "In the present study, we demonstrated that POU3F3 enhanced cancer cell proliferation, migration and invasion by downregulating miR-30d-5p in non-small cell lung cancer (NSCLC, adenocarcinoma), which was a major subgroup of lung cancer." (PMID 32615948, 2020). "The present study aimed to investigate the role of POU3F3 in non-small cell lung cancer (NSCLC)." (PMID 32615948, 2020).
prostate carcinoma (1 paper, 2021). A carcinoma that arises from epithelial cells of the prostate gland. "In prostate carcinoma, POU3F3 promotes cancer cell proliferation by upregulating ROCK1." (PMID 35201451, 2021).
renal failure (1 paper, 2016). "In particular, elongation and differentiation of the TAL and development of MD cells were impaired, and homozygous Pou3f3 knock-out mice died within 24 hours after birth due to renal failure." (PMID 27420727, 2016). "New-born homozygous Pou3f3 knock-out mice exhibit increased plasma urea and potassium levels and die from renal failure within 24 hours after birth." (PMID 27420727, 2016). "Deficiency of POU3F3 in knock-out mice leads to underdevelopment of the TAL, lack of differentiation of TAL cells, and perinatal death due to renal failure." (PMID 27420727, 2016).
Snijders Blok-Fisher syndrome (1 paper, 2023). An autosomal dominant neurodevelopmental disorder characterized by global developmental delay, hypotonia, intellectual disability, autistic features, impairments in speech and language skills, and dysmorphic features including abnormal, cupped, or prominent ears and ocular anomalies. "In conclusion, we report the first case of prenatal Snijders-Blok-Fisher syndrome caused by a de novo heterozygous truncating variant of POU3F3 in a fetus with transient isolated bilateral MV." (PMID 37593446, 2023).
Ventriculomegaly (1 paper, 2023). An increase in size of the ventricular system of the brain. "However, the truncating variants in POU3F3 have not been associated with ventriculomegaly." (PMID 37593446, 2023).
tumor (29 papers, 2015 to 2025). "H1299 POU3F3 knockout cells exhibited decreased tumor mass and Ki67 staining, indicating POU3F3 deficiency impaired tumor proliferation capacity in vivo." (PMID 39932442, 2025). "Instead, POU3F3 promotes tumor advancement and chemoresistance by transforming normal fibroblasts into cancer-associated fibroblasts." (PMID 40781643, 2025). "Mechanistically, the lncRNA POU3F3 can be packaged into tumor-secreted exosomes and transferred from ESCC cells to NFs, leading to the activation of NFs." (PMID 38540273, 2024). "Increased tumor growth was observed in the tumors of lncRNA POU3F3 overexpressing cells, and the xenografts showed a larger volume than the control group." (PMID 33816296, 2021). "Compared to normal tissues, POU3F3 expression level was significantly higher in tumor tissues (p < 0.05)." (PMID 35201451, 2021). "Expression levels of POU3F3 and microRNA-30d-5p (miR-30d-5p) in cancer and non-tumor tissues from these NSCLC patients were determined by qRT-PCR." (PMID 32615948, 2020). "The results of the present study demonstrate that tumor-secreted exosomal lncRNA POU3F3 can induce NF differentiation into CAFs." (PMID 32637576, 2020). "Our study focused on interactions between POU3F3 and miR-30d-5p in NSCLC, because our preliminary transcriptome analysis showed that expression levels of POU3F3 and miR-30d-5p were inversely correlated in tumor tissues of NSCLC patients." (PMID 32615948, 2020). "The results of qRT-PCR showed that, compared to adjacent healthy tissues, POU3F3 was significantly upregulated, while miR-30d-5p was significantly downregulated in tumor tissues (p < 0.05)." (PMID 32615948, 2020). "Taken together, these results indicate that tumor-secreted exosomal lncRNA POU3F3 facilitates the differentiation of NFs to CAFs." (PMID 32637576, 2020). "Correlation analysis showed that expression levels of POU3F3 and miR-30d-5p were inversely correlated in tumor tissues." (PMID 32615948, 2020). "Similar to DLX1, another m-homeobox gene POU3F3 has hypermethylation canyon in gene-body and aberrant overexpression in multiple tumor types including BLCA, LUSC, and UCEC." (PMID 30097071, 2018). "The expressions of both linc-POU3F3 and linc-H19 were significantly elevated in the CRC tissues compared with the adjacent non-tumor tissues (P < 0.01, Z = −3.684 for linc-POU3F3; P < 0.01, Z = − 3.805 for linc-H19)." (PMID 26510906, 2016). "Examination of the correlation between linc-POU3F3 expression and clinical pathological features showed that increased linc-POU3F3 expression correlated with the tumor histology grade and N grade." (PMID 26510906, 2016). "Our results demonstrated that plasma lncRNA POU3F3 was a promising tumor marker, which effectively supplemented the serum SCCA for ESCC detection." (PMID 25608466, 2015). "To further investigate the expression levels of POU3F3 protein in tumor samples, we conducted an immunoblotting assay to examine the POU3F3 protein expression in NSCLC tissues and corresponding paracancerous tissues from Nanhai Hospital of Traditional Chinese Medicine." (PMID 39932442, 2025). "Our xenograft experiment data show that mice injected with POU3F3 knockout H1299 cells exhibited a reduction in both tumor volume and weight, accompanied by a significant downregulation of Ki‐67 in the tumor tissue sample, indicating POU3F3 promotes cell proliferation and tumor growth in NSCLC." (PMID 39932442, 2025). "POU3F3 expression in paired tumor and healthy tissues was detected by RT-qPCR." (PMID 35201451, 2021). "Thus, MALAT-1 promotes tumor growth and migration and prevents tumor cell apoptosis, linc-POU3F3 induces angiogenesis, ZFAS1 promotes proliferation and migration of cancer cells." (PMID 30211160, 2018). "In addition, positive correlation between linc-POU3F3 expression and clinical parameters, including tumor grading and N stage were detected." (PMID 26510906, 2016).